CRY2 (cryptochrome circadian regulator 2)
Description:
Transcriptional repressor which forms a core component of the circadian clock. The circadian clock, an internal time-keeping system, regulates various physiological processes through the generation of approximately 24 hour circadian rhythms in gene expression, which are translated into rhythms in metabolism and behavior. It is derived from the Latin roots 'circa' (about) and 'diem' (day) and acts as an important regulator of a wide array of physiological functions including metabolism, sleep, body temperature, blood pressure, endocrine, immune, cardiovascular, and renal function. Consists of two major components: the central clock, residing in the suprachiasmatic nucleus (SCN) of the brain, and the peripheral clocks that are present in nearly every tissue and organ system. Both the central and peripheral clocks can be reset by environmental cues, also known as Zeitgebers (German for 'timegivers'). The predominant Zeitgeber for the central clock is light, which is sensed by retina and signals directly to the SCN. The central clock entrains the peripheral clocks through neuronal and hormonal signals, body temperature and feeding-related cues, aligning all clocks with the external light/dark cycle. Circadian rhythms allow an organism to achieve temporal homeostasis with its environment at the molecular level by regulating gene expression to create a peak of protein expression once every 24 hours to control when a particular physiological process is most active with respect to the solar day. Transcription and translation of core clock components (CLOCK, NPAS2, BMAL1, BMAL2, PER1, PER2, PER3, CRY1 and CRY2) plays a critical role in rhythm generation, whereas delays imposed by post-translational modifications (PTMs) are important for determining the period (tau) of the rhythms (tau refers to the period of a rhythm and is the length, in time, of one complete cycle). A diurnal rhythm is synchronized with the day/night cycle, while the ultradian and infradian rhythms have a period shorter and longer than 24 hours, respectively. Disruptions in the circadian rhythms contribute to the pathology of cardiovascular diseases, cancer, metabolic syndromes and aging. A transcription/translation feedback loop (TTFL) forms the core of the molecular circadian clock mechanism. Transcription factors, CLOCK or NPAS2 and BMAL1 or BMAL2, form the positive limb of the feedback loop, act in the form of a heterodimer and activate the transcription of core clock genes and clock-controlled genes (involved in key metabolic processes), harboring E-box elements (5'-CACGTG-3') within their promoters. The core clock genes: PER1/2/3 and CRY1/2 which are transcriptional repressors form the negative limb of the feedback loop and interact with the CLOCK|NPAS2-BMAL1|BMAL2 heterodimer inhibiting its activity and thereby negatively regulating their own expression. This heterodimer also activates nuclear receptors NR1D1/2 and RORA/B/G, which form a second feedback loop and which activate and repress BMAL1 transcription, respectively. CRY1 and CRY2 have redundant functions but also differential and selective contributions at least in defining the pace of the SCN circadian clock and its circadian transcriptional outputs. Less potent transcriptional repressor in cerebellum and liver than CRY1, though less effective in lengthening the period of the SCN oscillator. Seems to play a critical role in tuning SCN circadian period by opposing the action of CRY1. With CRY1, dispensable for circadian rhythm generation but necessary for the development of intercellular networks for rhythm synchrony. May mediate circadian regulation of cAMP signaling and gluconeogenesis by blocking glucagon-mediated increases in intracellular cAMP concentrations and in CREB1 phosphorylation. Besides its role in the maintenance of the circadian clock, is also involved in the regulation of other processes. Plays a key role in glucose and lipid metabolism modulation, in part, through the transcriptional regulation of genes involved in these pathways, such as LEP or ACSL4. Represses glucocorticoid receptor NR3C1/GR-induced transcriptional activity by binding to glucocorticoid response elements (GREs). Represses the CLOCK-BMAL1 induced transcription of BHLHE40/DEC1. Represses the CLOCK-BMAL1 induced transcription of NAMPT (By similarity). Represses PPARD and its target genes in the skeletal muscle and limits exercise capacity (By similarity). Represses the transcriptional activity of NR1I2 (By similarity).
Synonyms: HCRY2; PHLL2
Tractability: Small molecule: a high-quality ligand is known. Antibody: its Gene Ontology location is reachable by antibodies, with high confidence. PROTAC: UniProt records ubiquitination sites on it; ubiquitination databases record sites on it; a small molecule that binds it is known.
Gene: Protein-coding gene on chromosome 11 (45,847,118 to 45,883,248, forward strand). Ensembl gene ENSG00000121671.
Subcellular location: Cytoplasm; Nucleus
Subcellular location (Human Protein Atlas): Nuclear speckles; Cytosol
Pathways (Reactome):
Circadian clock: Degradation of CRY and PER proteins; Phosphorylated BMAL1:CLOCK (ARNTL:CLOCK) activates expression of core clock genes; Phosphorylation and nuclear translocation of the CRY:PER:kinase complex; Phosphorylation of CLOCK, acetylation of BMAL1 (ARNTL) at target gene promoters; The CRY:PER:kinase complex represses transactivation by the BMAL:CLOCK (ARNTL:CLOCK) complex
Gene Ontology:
Molecular function: damaged DNA binding; deoxyribodipyrimidine photo-lyase activity; DNA (6-4) photolyase activity; DNA binding; phosphatase binding; protein binding; protein phosphatase inhibitor activity; single-stranded DNA binding; blue light photoreceptor activity; FAD binding; transcription cis-regulatory region binding; kinase binding; nuclear receptor binding; protein kinase binding
Biological process: negative regulation of DNA-templated transcription; negative regulation of transcription by RNA polymerase II; photoreactive repair; regulation of sodium-dependent phosphate transport; response to light stimulus; blue light signaling pathway; circadian regulation of gene expression; circadian rhythm; entrainment of circadian clock by photoperiod; glucose homeostasis; negative regulation of circadian rhythm; negative regulation of nuclear receptor-mediated glucocorticoid signaling pathway; regulation of circadian rhythm; response to activity; lipid storage; negative regulation of glucocorticoid secretion; response to insulin
Cellular component: cytosol; extracellular region; nuclear speck; nucleus; Cry-Per complex; cytoplasm; mitochondrion
Genetic constraint (gnomAD): Loss-of-function variants: 31 observed, 70.14 expected, observed/expected ratio (o/e) 0.44, 90% interval 0.33 to 0.6. The upper end of that interval is the gene's LOEUF score, 0.6, which puts it in group 2 of 6, group 1 being the genes least tolerant of losing a copy. Missense variants: 606 observed, 804.07 expected, observed/expected ratio (o/e) 0.75, 90% interval 0.7 to 0.81. Synonymous variants: 303 observed, 318.58 expected, observed/expected ratio (o/e) 0.95, 90% interval 0.87 to 1.05.
Homologues: Orthologues: chimpanzee CRY2 (99% identical), macaque CRY2 (99% identical), pig CRY2 (96% identical), guinea pig CRY2 (96% identical), dog CRY2 (96% identical), rabbit CRY2 (96% identical), mouse Cry2 (94% identical), rat Cry2 (94% identical), tropical clawed frog cry2 (78% identical), zebrafish cry2 (70% identical). Paralogues in human: CRY1 (71% identical).
Diseases named in the same sentence as CRY2 in open-access papers:
CRY2 is named in the same sentence as 122 diseases in open-access papers, as found by Europe PMC text mining. Sharing a sentence is not in itself a finding about the gene and the disease. The quoted sentences say what the papers report.
breast carcinoma (38 papers, 2010 to 2025). "Altered Cry2 expression, however, is more likely to be associated with altered activity of established oncogenic or tumor suppressor pathways in breast cancer than Cry1." (PMID 37024472, 2023). "Studies have found that mutations in BMAL1, CRY1, and CRY2 are often associated with a higher risk and recurrence of acute myeloid leukemia and endometrial, ovarian, colorectal, and breast cancers." (PMID 34149816, 2021). "NSW increased risk of breast cancer in women who carried the heterozygote genotype of CRY2 rs2292912 (OR = 1.98, 95% CI = 1.14–3.44) or carried at least one minor allele of RORA rs1482057 (OR = 2.20, 95% CI = 1.10–4.37)." (PMID 31358835, 2019). "There are a few studies which focus on CRY1 and CRY2 polymorphism, but there are some significant gene variants associated with breast cancer risk." (PMID 31739444, 2019). "The G allele of CRY2 rs1401417 appeared to have a protective effect against breast cancer in “long term” shiftworkers (>2 years of shiftwork stratification)." (PMID 28177907, 2017). "CRY2 variant rs1041417 was strongly associated with premenopausal and with ER-positive in breast cancer patients by Dai and colleagues employing a dataset of Asian ethnicity." (PMID 28177907, 2017). "Breast cancer risk is also associated with single nucleotide polymorphisms (SNPs) in Npas2 and Cry2, as well as Clock." (PMID 27590298, 2016). "The key circadian genes, PERIOD 2 (PER2 variant 2), CLOCK, TIMELESS, CRYPTOCHROME 1 (CRY1) and CRYPTOCHROME 2 (CRY2) were all also significantly expressed in all breast cancer cell lines and all patients’ breast cancer tissues examined." (PMID 24683528, 2013). "Then, the dysregulation of the CRY2 leads to an increase in breast cancer risk and aggressiveness." (PMID 40003882, 2025). "In previous studies, Cry2 showed a significant decrease in breast cancer, and higher Cry2 expression was associated with a longer metastasis-free survival time, suggesting that this circadian protein may be a tumor suppressor in breast cancer." (PMID 37024472, 2023). "However, a significant association with breast cancer risk in postmenopausal patients for three SNPs in CRY2 has been found." (PMID 31739444, 2019). "Furthermore, lower expression levels of core circadian CRY2 gene in breast cancer tissues was associated with breast cancer advancement and the disease outcomes." (PMID 31151182, 2019). "Indeed, loss of PER3 and CRY2 co-expression is associated with a higher risk of breast cancer metastasis." (PMID 27590298, 2016). "Although both the Cry genes may be implicated in breast cancer development, the majority of findings thus far have pinpointed Cry2 as playing a more prominent role." (PMID 26220712, 2015). "The variants in CRY2 may affect breast cancer through the hormone signaling pathway." (PMID 31358835, 2019). "Polymorphisms in CLOCK, NPAS2, CRY2, RORA, TIMELESS, and ARNTL have been associated with breast cancer." (PMID 40534841, 2025). "As a circadian gene, CRY2's abnormal regulation leads to the disturbance of circadian rhythm, which can induce the development of cancers (like breast cancer) by affecting specific physiological functions such as signal transduction, cell division, and growth." (PMID 40487778, 2025). "CRY2 inhibits breast cancer cell proliferation, but its acetylation attenuates this antiproliferative effect." (PMID 41142939, 2025). "We found that ANXA2R protects against in situ breast cancer by reducing the expression of cathepsin F. PRX and CRY2 are protective factors for both cathepsin Z and in situ breast cancer." (PMID 39944834, 2025). "A systematical analysis of genomic profiling and clinical data showed significantly decreased Cry1 and Cry2 mRNA levels in multiple cancer types, including breast carcinoma, lung squamous cell carcinoma, thyroid carcinoma, and lung adenocarcinoma." (PMID 37024472, 2023).
breast carcinoma (continued). "Our analysis showed that four SNPs, including rs2292912 in CRY2, rs2253820 in PER1, rs2289591 in PER1 and rs3027188 in PER1, were significantly associated with breast cancer risk." (PMID 36672368, 2023). "Cry2 suppressed breast cancer proliferation through the NF-κB pathway, but acetylation of Cry2 attenuated this effect." (PMID 37024472, 2023). "In summary, this study revealed the effect of Cry2 itself and its acetylation on breast cancer cell proliferation and identified the regulatory enzymes of Cry2 acetylation." (PMID 37024472, 2023). "We found that p65 deletion abrogated the effect of Cry2 acetylation on breast cancer cell proliferation." (PMID 37024472, 2023). "In our study, Cry2 expression inhibited breast cancer cell proliferation, and acetylation of Cry2 reversed this effect." (PMID 37024472, 2023). "Here, we aimed to elucidate the post-translational regulations of Cry2 and its role in breast cancer pathogenesis." (PMID 37024472, 2023). "This is consistent with our finding that high Cry2 acetylation level promotes breast cancer proliferation." (PMID 37024472, 2023). "Meanwhile, rs2292912 in CRY2, rs2253820 in PER1, rs2289591 in PER1 and rs3027188 in PER1 were positively associated with the risk of breast cancer." (PMID 36672368, 2023). "Considering that Cry2 mainly represses transcriptional activation in cells, we analyzed the TCGA-BRCA database to explore the possible pathways, through which Cry2 suppresses breast cancer cell proliferation." (PMID 37024472, 2023). "Women with SNPs in CRY2, NPAS2, and CLOCK are at a higher risk of breast cancer, and PER2 suppresses estrogen receptor-dependent transcription." (PMID 35984550, 2022). "Breast cancer patients have higher methylation of the CRY2 promoter consistent with lower CRY2 expression and loss of PER3 and CRY2 co-expression increases metastasis risk." (PMID 35984550, 2022). "The expression levels of rhythm genes, such as CLOCK, PER1, PER2, PER3, CRY2, RORC and TIMELESS, are associated with the metastasis-free survival of breast cancer patients." (PMID 35180863, 2022). "Single nucleotide polymorphisms in the Cryptochrome Circadian Regulator 2 (CRY2) and CLOCK genes have also been shown to increase the risk of breast cancer." (PMID 36661673, 2022). "The CRY2 genotype of breast cancer patients has also been correlated with ER status, and PER3 loss is associated with recurrent ER+ tumors." (PMID 35163264, 2022). "Another study reported that the expression of CRY2 is decreased by the progression and prognosis of breast cancer." (PMID 33114496, 2020). "Other studies have revealed that PER1, PER2, PER3, and CRY2 expression are downregulated in breast cancer tissues, whereas CLOCK and TIMELESS expression are upregulated." (PMID 33114496, 2020). "Our analysis indicates that five SNPs, BMAL1 rs2279287, CLOCK rs12505266, CRY2 rs10838524, PER1 rs2735611, PER2 rs934945, are significantly associated with the breast cancer risk in the Polish association study." (PMID 31739444, 2019). "In this line, polymorphisms affecting CLOCK (rs3805151), CRY1 (rs1056560), CRY2 (rs1401417), and PER2 (rs934945) have been associated to breast cancer risk in a Chinese population." (PMID 30873119, 2019). "This case-control study analyzed the associations between breast cancer and polymorphisms in circadian clock genes (ARTNL, CLOCK, CRY2, NPAS, and PER2) and in genes of the melatonin pathway as well (AANAT and MTNR1B)." (PMID 30873119, 2019). "A recent study in breast cancer showed that circadian genes CRY2 and PER1-3 were down-regulated, while CLOCK and TIMELESS were over-expressed." (PMID 30873119, 2019). "The patients having at least one or more risk alleles (among three significant SNPs CRY2 rs10838524; PER1 rs2735611; PER2 rs934945) were significantly associated with an increased breast cancer risk OR = 1.66 (1.17–2.35) p = 0.005." (PMID 31739444, 2019).
breast carcinoma (continued). "Some studies have indicated similar results showing that genes PER1, PER2, PER3, and CRY2 were down-expressed in breast cancer tissues." (PMID 29958276, 2018). "A significantly decreased mRNA level in the breast cancer tissue samples was observed for CRY2 (β-coefficient -0.424, p<0.0001), PER1 (β-coefficient -0.371, p<0.0001), PER2 (β-coefficient -0.149, p = 0.037) and PER3 (β-coefficient -0.231, p = 0.001)." (PMID 29958276, 2018). "This clock–cancer link was confirmed in later studies which showed genetic associations between some variants of the clock genes NPAS2, CRY2 and CLOCK and the risk of breast carcinoma, prostate carcinoma and Non-Hodgkin lymphoma." (PMID 28177907, 2017). "In this material, the Cry2 promoter was found to be hypermethylated, whereas the Clock promoter was hypomethylated, two changes also present in breast cancer." (PMID 25310649, 2014). "Promoter hypomethylation in the oscillator gene Clock and promoter hypermethylation of Cry2 represent changes also detected in breast cancer." (PMID 25310649, 2014). "Here, we report findings from in vitro loss-of-function investigations into the phenotypic effects of CRY2 knockdown on cell cycle, apoptosis, and DNA damage response to mutagen challenge in a breast cancer cell line." (PMID 20334671, 2010). "Furthermore, Cry2 inhibited breast cancer development; however, Cry2 acetylation reversed this effect, demonstrating that circadian proteins and their post-translational modifications affect breast cancer progression." (PMID 37024472, 2023). "Furthermore, we found that Cry2 inhibits breast cancer proliferation, but its acetylation impairs this effect." (PMID 37024472, 2023). "Besides, rs2292912 in CRY2, rs2253820 in PER1, rs2289591 in PER1 and rs3027188 in PER1 were positively associated with the risk of breast cancer." (PMID 36672368, 2023). "Finally, bioinformatics analysis revealed that genes repressed by Cry2 in breast cancer were mainly enriched in the NF-κB pathway, and acetylation reversed this repression." (PMID 37024472, 2023). "In conclusion, Cry2 inhibits breast cancer cell proliferation via the NF-κB pathway." (PMID 37024472, 2023). "Low Cry2 acetylation level showed a stronger inhibition of breast cancer cell growth, which inhibited by HDAC6, consistent with a previous report showing that high HDAC6 expression was associated with higher survival in breast cancer patients." (PMID 37024472, 2023). "NF-κB promotion of cell proliferation via autophagy inhibition has been reported, and we also found that Cry2 could inhibit breast cancer proliferation." (PMID 37024472, 2023). "Meanwhile, rs2292912 in CRY2, rs2253820 in PER1, rs2289591 in PER1 and rs3027188 in PER1 could significantly increase the risk of breast cancer." (PMID 36672368, 2023). "Additionally, polymorphisms of rhythm genes, including BMAL1, CRY2, PER1, PER2 and PER3, are associated with susceptibility to breast cancer." (PMID 35180863, 2022). "The carriers who had at least one variant allele of BMAL1 rs2279297 (p = 0.05) or were a recessive homozygote of CRY2 rs3824872 (p = 0.0004), had a significantly decreased gene expression level in breast cancer tissue compared to the women with a dominant homozygous genotype." (PMID 31739444, 2019). "Other cryptochrome gene variants have previously been shown to be associated with a decreased breast cancer risk including GT genotype of rs1056560 in CRY1 (OR = 0.84 95% CI = 0.71–0.99) and CC genotype of rs1401417 in CRY2 (OR = 0.24 95% CI = 0.08–0.73) in premenopausal women." (PMID 31739444, 2019). "CRY2 may promote breast cancer aggressiveness, possibly via epigenetic modifications, and its degradation promotes chemoresistance in colorectal cancer." (PMID 27902487, 2017).